IL6 (interleukin 6)
Diseases named in the same sentence as IL6 in open-access papers (continued):
Sharing a sentence is not in itself a finding about the gene and the disease.
tumor (continued). "The cytokines interleukin-6 (IL-6) and tumor necrosis factor-alpha (TNF-α) promote inflammation and tumor progression in CRPC13,14." (PMID 37646236, 2023). "In our study, secretion of IL-6 by PB and Lenti CAR-T cells was unchanged at 4 hours after encountering tumor cells, however, Lenti CAR-T cells released much higher levels of IL-6 into the media than PB CAR-T cells at 24 hours." (PMID 37228617, 2023). "We found significant enrichment of immune-related signaling pathways in most tumor types, including TNFA-signaling-via-NFκB, IFN- γ response, IFN- α response, inflammatory response, IL6-JAK-STAT3, IL2-STAT5, and allograft-rejection." (PMID 37600783, 2023). "IFN-β, IL-6, CXCL10, CCL2, and CCL5 have been reported to be induced in tumor cells by ATRi plus RT in vivo and/or in vitro." (PMID 36810257, 2023). "The IL-6/JAK1 signaling pathway has been shown to positively regulate the stability of the PD-L1 protein and promote tumor immune escape." (PMID 37601051, 2023). "Our results showed that IL-6, IL-17, TNF-α, TLR-2 and TLR-4 genes were overexpressed in tumor tissues compared to adjacent normal tissues." (PMID 38075864, 2023). "It has been seen that CMF treatment enhances the IL-1β, IL-6, and TNF-α in the tumor-bearing animal." (PMID 37631080, 2023). "The expression levels of TNF-α, IL-6, and IL12p70 were upregulated in vivo and in vitro, and the infiltration of immune CD4 and CD8 T cells was detected in tumor tissues under laser irradiation." (PMID 37896250, 2023). "Secretion of IL-6 and IL-10 by SW620 and HCT116F3 cells were both undetectable, indicating the observed increase of IL-6 and IL-10 secretion in macrophage-tumour interaction came predominately from the macrophages." (PMID 37612278, 2023). "Increased tumour nodules were found in 9-month-old HDAC3LCKO&IL-6−/− male mice, and the average number of liver tumours per HDAC3LCKO&IL6−/− male mouse was 7, which was significantly smaller than that of the females." (PMID 37752418, 2023). "In a cross-sectional study of women with metastatic breast cancer, circulating tumor cells positively correlated with CRP (r=0.22; P=0.02) and IL6 (r=0.25; P=0.01)." (PMID 38148846, 2023). "In another study, MM-derived EVs were reported to modulate the STAT3 pathway in endothelial cells, not only promoting angiogenesis but also inducing tumor growth via the release of VEGF and IL-6, respectively." (PMID 37371477, 2023). "IL-6 is an important member of the cytokine network that mainly transmits signals through the STAT3 signaling pathway in cancer, thereby promoting tumor invasion and metastasis." (PMID 37981718, 2023). "Studies using a Drosophila melanogaster malignant tumour model have demonstrated that TNF and IL-6 mediated autophagy can modulate the tumor microenvironment and participate in tumor growth." (PMID 37313458, 2023). "In the present study, we found that the level of proinflammatory cytokines including IL-1β, IL-6 and TNF-α were significantly increased in tumor-bearing mice after DSF treatment." (PMID 37305383, 2023). "Our study reports that IL6, CA-125, and HE4 levels were higher in the group with tumor resectability of suboptimal > 1 cm." (PMID 37792745, 2023). "The first is the cytokines secreted by CAFs lead to anti-tumor therapy resistance, such as activated CAFs promoting cancer cell resistance to CDDP by secreting IL-6." (PMID 37666813, 2023). "A significant negative correlation was observed between miR-181a levels and IL6 and IL12B in tumor tissues from patients diagnosed with TNBC." (PMID 37932806, 2023). "In our previous study, the transcriptional level of KDM2A was increased in normal fibroblasts after stimulation with tumor-derived inflammatory cytokines TNF-α and IL-6 and further drove the transformation of the cells into CAFs." (PMID 37821959, 2023). "The IL-6/STAT3/Twist pathway is critically important in the development of cancer, and impacting tumour cell growth, proliferation, and migration." (PMID 37742025, 2023).
tumor (continued). "We found that IL-6 induced both STAT3 activation and tumor proliferation in SBC-3 and SBC-5 cells using western blotting analysis and a WST-8 assay." (PMID 36961655, 2023). "In HNSCC, tumor cells can recruit and drive macrophages to M2 phenotype by producing C–C chemokine ligand 2 (CCL2)/ CC chemokine receptor 2 (CCR2), IL-6, and IL-10." (PMID 37024932, 2023). "TAMs, abundant components in the TME, release several cytokines and chemokines like IL‐6, CCL18, and IL‐8 for interacting with their respective receptors on cancer cells, thus activating oncogenic pathways and inducing tumor malignancy." (PMID 37846367, 2023). "More importantly, IL-6 in turn increased the EIF4A3 and CCL2 levels within tumor cells in a positive feedback mechanism, further enhancing tumor cSERPINE2 biogenesis and promoting the recruitment of TAMs." (PMID 36797769, 2023). "IL-33 can affect the barrier function of the intestine leading to increased translocation of bacterial products and inducing the production of pro-tumorigenic cytokines, such as IL-6, by immune cells that activate STAT3, thereby promoting tumor growth." (PMID 37296602, 2023). "TREM1 similarly appears to amplify the inflammatory response, including production of IL-6; blockade of TREM1 has reportedly attenuated tumor growth in an experimental PDAC model." (PMID 38028629, 2023). "Tumor-derived PTHrP circulates and triggers PTH1R on osteoblasts, leading to the expression of VEGF-A and IL6." (PMID 37085481, 2023). "Conversely, levels of apelin, CCL2, progranulin, interleukin-6, chemerin, retinol binding protein 4 (RBP4), resistin, and plasminogen activator inhibitor-1 (PAI-1) expression were lower in tumor tissue than in adjacent normal tissue." (PMID 36917086, 2023). "Tumor cells secrete cytokines, growth factors, and chemokines such as TGF-β, CXCL12, PDGF, FGF, and IL-6 that trigger the MSCs to differentiate into CAFs." (PMID 37626931, 2023). "The PGF2 tumor phenotype has elevated CCL2, IL6, IL1A, and IL1B, all of which are secreted by uterine smooth muscle cells treated with PGF2." (PMID 36834607, 2023). "CAAs increase the secretion of IL-6, which increases ATGL expression in BC cells and facilitates lipolysis in tumor cells to produce FAs as energy resources and material for macromolecule synthesis, which promotes BC aggressiveness." (PMID 36765683, 2023). "Among them, STAT3 and NF-κB pathways are strongly activated so that IL-6 and CXCL8 act synergistically to promote the proliferation of tumor cells." (PMID 37700840, 2023). "HMGB1 upregulation and the successive overexpression of IL-23, IL-17 and IL-6, followed by STAT3 activation, promotes tumor growth." (PMID 37772080, 2023). "The cytokine IL-6 was found to be a crucial regulator of MDSC accumulation, activation, and differentiation in vitro as well as a factor promoting tumour cell proliferation, survival, invasiveness, and metastasis." (PMID 36161514, 2023). "Pro-tumorigenic chemo/cytokines such as IL-6, IL-10, CCL2, and CCL5 were decreased in NLRC5+ tumor-bearing ascites, correlating with significantly decreased frequency of tolerogenic DC2s subsets in this compartment." (PMID 38235131, 2023). "IL-6 and VEGF have been further characterized as cytokines that stimulate tumor growth and metastasis, while others, such as IFN-γ, can exert anti-NB activity by inducing tumor cell apoptosis and by inhibiting angiogenesis." (PMID 37239815, 2023). "On the other hand, hypoxic tumor cells produce cytokines, such as oncostatin, TGF-b, or IL-6, which provoke TAMs’ alternative (M2) activation." (PMID 37345046, 2023). "PPAT secrets multiple kinds of cytokine, including IL-6, TNF-ɑ and MMP9, which participates in the development of tumour growth and invasiveness." (PMID 37042512, 2023). "IL6 can promote tumor-cell proliferation, survival, invasiveness, and metastasis, while IL8 correlates with an immunosuppressive tumor microenvironment resulting in adverse cancer prognosis." (PMID 36860652, 2023).
tumor (continued). "Blocking the IL-6 pathway of signaling in CAFs led to a restoration of CD8+ T cells and hindered tumor growth." (PMID 36980785, 2023). "M1 macrophages promote tumor destruction and produce TNF and interleukin-6, while M2 macrophages contribute to tumor progression by producing VEGF, MMP, and interleukin-10." (PMID 37280670, 2023). "IL-6 is increased in PCa, induces EMT and metastasis, increases the expression of androgen receptor, and induces infiltration of T cells into the tumour microenvironment." (PMID 38137361, 2023). "Because of the high metabolic activity of adipose tissue, pro-inflammatory factors such as interleukin (IL)-6 and tumor necrosis factor (TNF)-alpha secreted by this tissue can initiate tumor formation." (PMID 36860687, 2023). "For example, large numbers of cytokines and growth factors that stimulate angiogenesis, including VEGF, FGF-2, βFGF, PDGF, IL-8, IL-6, angiopoietin, and TGF, are released by MSCs and contribute to the development of tumor angiogenesis." (PMID 36829187, 2023). "The IL-6/STAT3 signaling pathway can effectively trigger EMT and increase the number of tumor stem cells." (PMID 37857728, 2023). "For example, inflammatory SASP such as CCL3 and IL-6 remodels the TME by recruiting immunosuppressive cells, thus protecting tumor cells from immunosurveillance." (PMID 36675039, 2023). "TNFα production in OC leads to increases in IL6, VEGF, C-C motif ligand 2 (CCL2), and C-X-C motif chemokine ligand 12 (CXCL12), and lower levels of TNF-α lead to a reduction in tumor growth." (PMID 37445860, 2023). "The logFC of CD80 and IL-6 was 1.433 and 1.233, respectively, suggesting that CD80 and IL-6 were upregulated in HGSOC tumor issues." (PMID 37124547, 2023). "These ingredients can potentially decrease the levels of inflammatory cytokines (such as IL-6 and TNF-α), inhibit the expression of tumor-related factors (such as JAK2/STAT3, MMP-9, and vimentin), and increase immune cell activity." (PMID 37742025, 2023). "IL‐6 upgrades miR‐25‐3p through STAT3/c‐MYC signaling to downgrade PTPRO in HCC monocytes, ascending PD‐L1 expression and tumor growth in vivo." (PMID 38098217, 2023). "In general, IL-6 promoted tumor cell migration and invasion by enhancing the EMT properties of tumor cells." (PMID 36614179, 2023). "Heteroctenus junceus scorpion venom, depending on the concentration and incubation time, promotes a decrease in the cytokines IL-6, IL-1β and IFN-γ; as well as an increase in TNF-α and IL-12 in the supernatant of the F3II tumor cells." (PMID 38137888, 2023). "Interaction of BCSC with macrophages initiates their tumor-promoting function, and these TAM produce high levels of IL6 which in turn initiates activation of the STAT3 signaling pathway and consequent enrichment of BCSC." (PMID 37445860, 2023). "Rosuvastatin was reported to inhibit pro-inflammatory cytokines including tumor necrosis factor-α (TNF-α), IL6, and TGF-β in mice, leading to tumor shrinkage." (PMID 36986550, 2023). "M2-like TAMs can produce a series of Th2 cytokines that promote GBM immune escape, together with cytokines that directly promote tumor cell proliferation such as IL-1β, TNF-α, and IL-6." (PMID 36923251, 2023). "On the other hand, the results showed that, for LUSC tumor samples, CDH2, SPP1, and TNC were significantly upregulated and FN1, CYR61, SERPINA1, and IL6 were significantly downregulated compared to their respective controls." (PMID 37887075, 2023). "In preclinical tumor models, blocking IL6R or gene ablation of intrinsic IL-6 signaling in CTLs, in combination with anti-PD-L1 therapy, enhances the anti-tumor CTL response, and improves tumor control." (PMID 37240834, 2023). "Sulindac inhibits the bioactivity of IL-6, TGF-α, and TGF-β, while also reducing the number of macrophages in the tumor microenvironment." (PMID 37830595, 2023).
tumor (continued). "Further comparison of immune infiltration, tumor mutation load, and immunophenoscore (IPS) comparison between the 2 groups indicates that the high-risk group could potentially demonstrate a heightened sensitivity towards immunotherapy checkpoints PD-1, CTLA-4, IL-6, and LAG3 in ccRCC patients." (PMID 37653791, 2023). "In this study, we focused on interleukin (IL)-6, soluble IL-2 receptor (sIL-2R) and tumor necrosis factor (TNF)-α as cytokines related to tumor immunity and microenvironment." (PMID 37733188, 2023). "Experiments in vitro verified that rhIL-37 reduced IL-6, pSTAT3Y705, cyclin D1, and HIF-1α levels that contributed to tumor cells proliferation and migration, and Bcl-2 level that inhibited apoptosis in A498 and Caki-1 cells." (PMID 37928545, 2023). "We found that a significant gradient toward the serum (CXCL9, IL6, IL10, IL13) or the tumor tissue (IL1B) exists for all cytokines in question." (PMID 36980700, 2023). "Specifically, IL‐6 can induce NF‐κB in GBM, resulting in the activation of signal transducer and activator of transcription 3 (STAT3) and increased tumor aggressiveness." (PMID 36627748, 2023). "Taken together, these findings indicate that serum sTIE2, PlGF, IL-6, IL-8, and TNF-α are biomarkers of tumor progression, vascular abnormalities, and immune suppression in GC." (PMID 37577519, 2023). "GOG-218 was the source of several articles identifying several potential predictors for response to anti-angiogenetic therapy: plasmatic concentrations of VEGF and VEGF-R2, tumor VEGF-A expression, micro-vessel density (MVD) and IL-6 levels." (PMID 36980348, 2023). "Of note, CAF-derived IL-6 can induce CD73( +)γδ Tregs to differentiate and secrete more adenosine, thereby establishing a positive feedback loop that greatly weakens the anti-tumor effects of CD8 + T cells and leads to a worse prognosis in patients." (PMID 37723510, 2023). "WAT wasting is driven by combinatorial action of tumor-secreted and/or host-secreted factors, such as tumor necrosis factor-α (TNF-α), interleukin-6 (IL-6) or IL-1β, which are transported through the bloodstream." (PMID 37749321, 2023). "At the same time, serum levels of proinflammatory cytokines such as CCL2, IL‐6, and MIP‐1β were also significantly elevated, indicating an enhancement of the systemic anti‐tumor immune response after P5091@RMPs‐R4F treatment." (PMID 36698296, 2023). "IL-6 induces the activation of STAT3 and NF-κB by CRP and specific acute phase response proteins, preventing apoptosis and thus promoting tumor cell proliferation." (PMID 37719018, 2023). "Another pathway often seen in cancers is IL6-JAK-STAT3, which is a proliferative driver often implicit in OvCa angiogenesis and tumour metastasis." (PMID 37444459, 2023). "The possible mechanisms by which M2 polarization promotes tumor progression and regulates TME involve secretion of growth factors and cytokines, such as IL6 and CCL18." (PMID 36334221, 2023). "For example, it was found that IL-6 promotes tumor progression by activating the MAPK pathway, which is known to induce tumor proliferation." (PMID 37373544, 2023). "Our results reveal that adenosine‐A2B signalling in Olaparib‐resistant cells induces IL‐6 secretion and subsequent STAT3 activation, which promotes tumour cell growth." (PMID 37278400, 2023). "Thus, cytokines secreted by IL-1β-activated CAFs, including IL-1 itself, IL-6 and IL-8, might favor the differentiation and proliferation of Th17 cells, as well as their recruitment to the tumor niche, which would ultimately favor tumor progression." (PMID 37460545, 2023). "The inflammatory cytokines including IL-1β, IL-6, IL-8, and CCL-5 that are induced by NF-kB promote tumor growth through the induction of cell proliferation." (PMID 37340387, 2023).
tumor (continued). "MSCs secrete a variety of angiogenesis promoting factors, such as VEGF, PDGF, IL-6, IL-8, angiopoietin-1, HGF and BDNF, to improve the regeneration of blood vessels, which is reasonably postulated to promote the tumor growth." (PMID 37957675, 2023). "Moreover, YAP/TAZ mobilize myeloid-derived suppressor cells (MDSCs) and tumor-associated macrophages (TAMs) by upregulating various cytokines, including C-X-C motif chemokine 5 (CXCL5), C-C motif chemokine 2 (CCL2), macrophage colony-stimulating factor 1 (CSF1), and interleukin-6 (IL6)." (PMID 38067201, 2023). "Consistently, the NF-κB target genes such as IL-6 and TNF were highly increased in both non-tumor and tumor areas of the ITF2ΔIE mice in contrast with the littermates." (PMID 37185280, 2023). "Low passage tumor alone secreted high concentrations of CCL2/MCP1, CXCL8/IL-8, CXCL1/GRO, IL-6, CXCL10/IP10, G-CSF, TGFβ1, MMP1, CCL3/MIPα, GM-CSF and EGF." (PMID 37063842, 2023). "Cancer cell-derived EVs often induce the secretion of EMMPRIN, MMP-9, and IL-6 from human monocytic cell lines, thereby modulating the ECM to promote migration and inflammation, ultimately leading to tumor progression." (PMID 37371477, 2023). "CAF-secreted IL-6 reduced NK cells' function in CRC cells by promoting monocyte differentiation into M2 macrophages and recruiting to the tumor." (PMID 37480115, 2023). "In OC, IL6 can activate the JAK/STAT3 signaling pathway, leading to tumor growth, metastasis, and EMT." (PMID 37445860, 2023). "In our experimental setting, we found that TAMCs release an increased amount of the pro-inflammatory cytokines IL-6 and TNF- α comparing to MC in tumor-free tissue, suggesting a pro-tumorigenic activity." (PMID 37730723, 2023). "Activation of the IL-6/JAK2/STAT3 signaling pathway is involved in the development and progression of tumors and contributes to the formation of the tumor inflammatory microenvironment." (PMID 37817809, 2023). "Humanization of the interleukin 6 locus in MISTRG6 mice enhances HSPC engraftment, making it feasible to model tumor-immune interactions in an autologous manner from a bedside bone marrow aspirate." (PMID 37487666, 2023). "In lung small cell lung cancer, the expression of genes involved in chemotaxis, including CCL2, CCL18, IL-6, adhesion molecule ICAM-1, and antigen presenting complex MHCI/II in tumor ECs are down-regulated." (PMID 36901858, 2023). "IL-6 and CXCL8, important autocrines in TNBC, were known to activate neutrophils and NK cells migration to the tumor." (PMID 37334114, 2023). "In the tumor microenvironment, IL-6 can also promote the immunosuppressive functions of MDSCs and macrophages, and can directly inhibit NK cells and CD8+ CTL cells, resulting in a tumor-suppressive immune microenvironment." (PMID 37644468, 2023). "This process enhances the secretion of cytokines such as IL-6, promotes anti-tumor immune response, remodels the immunosuppressed TME, and kills tumor cells." (PMID 37854883, 2023). "In a previous study of our group, we identified raloxifene to exert an inhibitory effect on IL-6/gp130/STAT3 signaling in PDAC cells and on tumor growth in a xenograft mouse model." (PMID 36495330, 2023). "Levels of inflammatory cytokines and chemokines, including IL-6 and CCL2, in tumor cells increased in serum globular tumor tissues, which showed an increase in tumor cells." (PMID 37639070, 2023). "Pro-inflammatory cytokines, such as IL-1α, IL-1β, IL-6, and TNF, showed higher amounts in the saliva of patients with OSCC, indicating the involvement of the inflammatory environment in tumor progression." (PMID 37686462, 2023). "We then analyzed the trend of cancer-promoting factors involved in tumor/stroma crosstalk, such as FGF2, and IL-6, this last systemically elevated in HNSCC patients, linked to resistance to therapy and secreted from stromal fibroblasts in several cancer types." (PMID 36979155, 2023).